LMLN (leishmanolysin like peptidase)
Description:
Metalloprotease.
Synonyms: Gp63; Msp; LMNL1; INV; IX14
Tractability: PROTAC: its protein half-life has been measured.
Gene: Protein-coding gene on chromosome 3 (197,960,200 to 198,043,720, forward strand). Ensembl gene ENSG00000185621.
Subcellular location: Cytoplasm; Lipid droplet
Subcellular location (Human Protein Atlas): Cytosol; Focal adhesion sites
Gene Ontology:
Molecular function: peptidase activity; metalloendopeptidase activity
Biological process: cell adhesion; proteolysis
Cellular component: cytoplasm; cytosol; lipid droplet; membrane
Genetic constraint (gnomAD): Loss-of-function variants: 35 observed, 46.53 expected, observed/expected ratio (o/e) 0.75, 90% interval 0.57 to 1. The upper end of that interval is the gene's LOEUF score, 1, which puts it in group 4 of 6, group 1 being the genes least tolerant of losing a copy. Missense variants: 421 observed, 471.44 expected, observed/expected ratio (o/e) 0.89, 90% interval 0.82 to 0.97. Synonymous variants: 174 observed, 182.87 expected, observed/expected ratio (o/e) 0.95, 90% interval 0.84 to 1.08.
Homologues: Orthologues: chimpanzee LMLN (99% identical), macaque LMLN (98% identical), rabbit LMLN (93% identical), pig LMLN (92% identical), dog LMLN (91% identical), mouse Lmln (89% identical), rat Lmln (86% identical), guinea pig LMLN (84% identical), tropical clawed frog lmln (68% identical), zebrafish lmln (66% identical), Drosophila melanogaster Invadolysin (39% identical), Caenorhabditis elegans Y43F4A.1 (35% identical).
Diseases named in the same sentence as LMLN in open-access papers:
LMLN is named in the same sentence as 16 diseases in open-access papers, as found by Europe PMC text mining. Sharing a sentence is not in itself a finding about the gene and the disease. The quoted sentences say what the papers report.
cancer (2 papers, 2015 to 2023). A tumor composed of atypical neoplastic, often pleomorphic cells that invade other tissues. "Metallopeptidases are known to play a role in cancer, however, it is not known if LMLN is directly implicated in tumorigenesis." (PMID 26497854, 2015). "The second mutated gene in S1 was CDH17, which has been shown to promote tumorigenesis and metastasis through Wnt-signaling and the third, the LMLN gene, which encodes a zinc-metallopeptidase, has not previously been implicated in cancer." (PMID 26497854, 2015).
tumor (1 paper, 2025). "Spearman correlation analysis supported these associations, showing positive correlations between risk scores and tumor stage, grade, invasion percentage, and expression of RAB10, PRKAA2, and LMO3, and negative correlations with BMI, survival time, and LMLN expression." (PMID 40804485, 2025).
LMLN also shares sentences with these, for which no sentence is quoted: infection (77 papers); leishmaniasis (16); visceral leishmaniasis (8); cutaneous leishmaniasis (5); parasite infection (3); melanoma (2); parasite (2); Chagas disease (1); co-infection (1); Granuloma (1); hepatic granuloma (1); poliovirus infection (1); skin infection (1); Splenomegaly (1).